RNU4-83P (RNA, U4 small nuclear 83, pseudogene)
Gene: Small nuclear RNA gene on chromosome 8 (100,831,728 to 100,831,860, reverse strand). Ensembl gene ENSG00000222795.
Homologues: Orthologues: chimpanzee U4 (100% identical), macaque U4 (90% identical). Paralogues in human: RNU4-10P (79% identical), RNU4-32P (79% identical), RNU4-49P (77% identical), RNU4-79P (75% identical), RNU4-15P (74% identical), RNU4-81P (74% identical), RNU4-17P (73% identical), RNU4-50P (71% identical), RNU4-28P (70% identical), RNU4-51P (68% identical), RNU4-90P (66% identical), RNU4-46P (65% identical), and 81 more.